FAM72A (family with sequence similarity 72 member A)
Description:
May play a role in the regulation of cellular reactive oxygen species metabolism. May participate in cell growth regulation.
Synonyms: LMPIP; UGENE; MGC57827; RP11-312O7.1; p17
Tractability: Antibody: the Human Protein Atlas places it where antibodies can reach. PROTAC: ubiquitination databases record sites on it.
Gene: Protein-coding gene on chromosome 1 (206,186,179 to 206,204,414, reverse strand). Ensembl gene ENSG00000196550.
Subcellular location: Cytoplasm; Mitochondrion
Subcellular location (Human Protein Atlas): Vesicles; Cytosol; Plasma membrane
Gene Ontology:
Molecular function: protein binding
Cellular component: cytosol; cytoplasm; mitochondrion
Genetic constraint (gnomAD): Loss-of-function variants: 1 observed, 6.53 expected, observed/expected ratio (o/e) 0.15, 90% interval 0.053 to 0.73. That is too few expected variants to judge how well the gene tolerates losing a copy. Missense variants: 14 observed, 77.23 expected, observed/expected ratio (o/e) 0.18, 90% interval 0.12 to 0.28. Synonymous variants: 4 observed, 24.33 expected, observed/expected ratio (o/e) 0.16, 90% interval 0.08 to 0.38.
Homologues: Orthologues: chimpanzee FAM72A (100% identical), macaque FAM72A (100% identical), guinea pig Fam72a (93% identical), mouse Fam72a (90% identical), rat Fam72a (90% identical), dog FAM72A (79% identical), zebrafish FAM72A (63% identical), tropical clawed frog fam72a (54% identical). Paralogues in human: FAM72B (99% identical), FAM72D (99% identical), FAM72C (98% identical).
Diseases named in the same sentence as FAM72A in open-access papers:
FAM72A is named in the same sentence as 39 diseases in open-access papers, as found by Europe PMC text mining. Sharing a sentence is not in itself a finding about the gene and the disease. The quoted sentences say what the papers report.
glioma (4 papers, 2023 to 2024). A benign or malignant brain and spinal cord tumor that arises from glial cells (astrocytes, oligodendrocytes, ependymal cells). "Family with sequence similarity 72 member A (FAM72A) is significantly upregulated in gliomas, significantly correlated with WHO grades, and associated with poor clinical outcomes." (PMID 39639571, 2024). "For example, FAM72A promotes glioma progression by participating in the induction of mitochondrial division and phagocytosis in gliomas." (PMID 39012280, 2024). "FAM72A has been shown to regulate mitophagy through the Pink1/Parkin signaling pathway, thereby promoting the progression of glioma." (PMID 39639571, 2024). "FAM72A was frequently upregulated in glioma tissues, and knockdown of FAM72A suppressed tumor progression." (PMID 37151394, 2023). "The results showed that, compared to the vector control, overexpression of FAM72A significantly increased tumor growth in glioma patients." (PMID 37151394, 2023). "FAM72A mediates glioma mitochondrial fission, induces mitophagy, and promotes glioma progression via mitophagy." (PMID 37151394, 2023). "Next, we detected the protein and mRNA expression levels of FAM72A in normal brain tissue (NBT) as well as different grades of glioma tissue." (PMID 37151394, 2023). "The data demonstrated that, compared to the vector control, knockdown of FAM72A clearly inhibited tumor growth in glioma patients." (PMID 37151394, 2023). "Based on the role of FAM72A in mitochondrial dynamics, mitochondrial morphology in glioma was analyzed using confocal and transmission electron microscopy." (PMID 37151394, 2023). "Subsequent mechanistic studies indicated that FAM72A promoted glioma progression by regulating mitophagy through the Pink1/Parkin signaling pathway." (PMID 37151394, 2023). "Consistent with previous reports, we found that FAM72A-mediated mitophagy can promote glioma progression to maintain mitochondrial homeostasis." (PMID 37151394, 2023). "In this study, glioma was demonstrated to have higher FAM72A expression and distinct mitochondrial morphology." (PMID 37151394, 2023). "Mechanistically, we found that FAM72A promoted glioma progression by regulating mitophagy through the Pink1/Parkin signaling pathway." (PMID 37151394, 2023). "Herein, FAM72A was demonstrated to promote immune evasion of glioma by upregulating PD-L1 expression." (PMID 37151394, 2023). "In conclusion, our study highlighted the importance of FAM72A in modulating glioma, thereby promoting glioma development." (PMID 37151394, 2023). "Taken together, these results demonstrated that the overexpression of FAM72A facilitated the progression of glioma." (PMID 37151394, 2023). "Taken together, these data indicated that the knockdown of FAM72A suppressed the progression of glioma." (PMID 37151394, 2023). "Taken together, these data indicated that FAM72A promoted glioma progression via mitophagy." (PMID 37151394, 2023). "In functional assays, FAM72A was shown to promote glioma cell growth." (PMID 37151394, 2023). "In summary, these results indicated that FAM72A promoted the glioma mitochondrial fission." (PMID 37151394, 2023). "In addition, we examined the correlation between FAM72A mRNA levels and clinicopathological characteristics in 65 glioma specimens." (PMID 37151394, 2023). "In this study, we report the clinical relevance and function of FAM72A in gliomas." (PMID 37151394, 2023). "The IHC intensity of FAM72A was clearly greater in glioma tissue, particularly in HGG versus NBT." (PMID 37151394, 2023). "Finally, FAM72A was found to promote the immune escape of glioma by upregulating PD-L1 expression." (PMID 37151394, 2023). "Overall, our data indicated that FAM72A may be a potential biomarker for glioma." (PMID 37151394, 2023). "Targeting FAM72A might represent a new therapeutic strategy for glioma." (PMID 37151394, 2023). "We sought to determine whether FAM72A promotes glioma progression by promoting mitophagy." (PMID 37151394, 2023).
glioma (continued). "Thus, FAM72A may be a useful biomarker for identifying and treating patients with glioma." (PMID 37151394, 2023). "However, neither FAM72A nor its function in glioma has yet been reported, and whether FAM72A contributes to tumor progression through Pink1/Parkin signaling remains unknown." (PMID 37151394, 2023).
lung carcinoma (4 papers, 2022 to 2023). "The enforced expression of FAM72A promoted lung cancer cell proliferation as indicated by a CCK assay." (PMID 36613817, 2022). "The expression of GRM8, SPC25, and FAM72A was negatively correlated with favorable outcomes and also observed in other cancer types such as lung cancer and breast cancer." (PMID 35368665, 2022). "One study reported that FAM72A expression was significantly increased in human lung cancer, and FAM72A is a potential molecular marker for a poor prognosis." (PMID 36483027, 2022). "Previous studies have shown that FAM72A is associated with the occurrence, development, and prognosis of various malignant tumors in nonneural tissues, such as colon, breast and lung cancers." (PMID 36483027, 2022). "Finally, we performed in vitro experiments to verify the function of FAM72A in lung cancer." (PMID 36613817, 2022). "The overexpression of FAM72A promoted proliferation and colony formation and also facilitated the EMT and migration of lung cancer cells." (PMID 36613817, 2022).
breast carcinoma (3 papers, 2022 to 2025). "In conclusion, by using a paralogue specific qPCR assay, we confirm that FAM72A, B, and D are overexpressed in colon and breast cancers, supporting previous studies that relied on analyzing publicly available databases." (PMID 40604025, 2025). "The family with sequence similarity 72 Member A (FAM72A), also known as Ugene, was initially identified in malignant colon cancers and overexpressed in several other common cancers, including breast cancer, lung cancer, uterus, and ovary cancer." (PMID 36613817, 2022).
hepatocellular carcinoma (3 papers, 2022 to 2025). A malignant tumor that arises from hepatocytes. "Additionally, FAM72A has been identified as a new prognostic factor for patients with hepatocellular carcinoma." (PMID 37275958, 2023).
acute myeloid leukemia (1 paper, 2022). Acute myeloid leukemia (AML) is a group of neoplasms arising from precursor cells committed to the myeloid cell-line differentiation. "Regarding stromal score, a positive correlation with FAM72A expression was seen in THCA, PCPG, PRA, acute myeloid leukemia (LAML), LGG, KIRP, KIRC, and a negative correlation in BRCA, UCEC, STAD, testicular germ cell tumors (TGCT), LUSC, and HNSC." (PMID 36613817, 2022).
adrenocortical carcinoma (1 paper, 2022). "Additionally, FAM72A expression levels increased with tumor progression in adrenocortical carcinoma (ACC), BLCA, CESC, kidney chromophobe (KICH), LUAD, kidney renal clear cell carcinoma (KIRC), and kidney renal papillary cell carcinoma (KIRP)." (PMID 36613817, 2022).
brain glioma (1 paper, 2023). A malignant glioma that involves the brain. "We first measured the levels of FAM72A protein expression in two human brain gliocyte cell lines (HA and NHA) as well as five human brain glioma cell lines (A-172, LN-18, U-251, LN-229 and U-87MG)." (PMID 37151394, 2023).
endometrial cancer (1 paper, 2023). Primary or metastatic malignant neoplasm involving the endometrium (mucous membrane that lines the endometrial cavity). "Our results showed that the expression levels of FAM13C, FAM72A and FAM11B were all significantly upregulated in endometrial cancer cells compared to normal endocervical cells." (PMID 37275958, 2023).
glioblastoma (1 paper, 2022). The most malignant astrocytic tumor (WHO grade IV). "Previous bioinformatic analysis indicated that FAM72A was involved in lung adenocarcinoma and glioblastoma multiforme (GBM)." (PMID 36613817, 2022).
liver cancer (1 paper, 2022). An epithelial or non-epithelial malignant neoplasm that arises from the liver. "High FAM72A expression was confirmed to be significantly enriched in the signature of “liver cancer proliferation”." (PMID 36483027, 2022).
lung adenocarcinoma (1 paper, 2022). A carcinoma that arises from the lung and is characterized by the presence of malignant glandular epithelial cells. "After all, we also performed a functional analysis to validate the oncogenic role of FAM72A on lung adenocarcinoma." (PMID 36613817, 2022). "We also investigated the functional role of FAM72A in lung adenocarcinoma (LUAD)." (PMID 36613817, 2022). "Functional analysis demonstrated that FAM72A played a tumor-promoting role in lung adenocarcinoma." (PMID 36613817, 2022).
mesothelioma (1 paper, 2022). A usually malignant and aggressive neoplasm of the mesothelium which is often associated with exposure to asbestos. "The results showed that high FAM72A levels were associated with poor OS in ACC, KIRC, KIRP, liver hepatocellular carcinoma (LIHC), LUAD, mesothelioma (MESO), uterine corpus endometrial carcinoma (UCEC), and uveal melanoma (UVM), but had a favorable OS with thymoma (THYM)." (PMID 36613817, 2022).
microcephaly (1 paper, 2021). A congenital or acquired developmental disorder in which the circumference of the head is smaller than normal for the person's age and sex. "This suggests that FAM72A could be an interesting candidate gene to potentially cause microcephaly when deleted or mutated." (PMID 34063381, 2021). "As the four FAM72 genes show very high homology to each other, it is likely that FAM72B-D fulfills similar roles as FAM72A in human brain development and maybe also in microcephaly." (PMID 34063381, 2021).
pancreatic adenocarcinoma (1 paper, 2022). "Moreover, a univariate Cox regression analyses identified high FAM72A as a risk factor for OS in ACC, KICH, KIRC, KIRP, brain lower grade glioma (LGG), LIHC, LUAD, MESO, pancreatic adenocarcinoma (PAAD), UCEC, and UVM, but a protective factor for overall survival (OS) in THYM." (PMID 36613817, 2022).
primary immunodeficiency (1 paper, 2022). "In THYM, FAM72A was associated with G2M checkpoint, MTORC1 signaling, MYC targets v1, DNA replication, two DNA repair pathways, oxidative phosphorylation, and primary immunodeficiency." (PMID 36613817, 2022).
thyroid carcinoma (1 paper, 2022). "FAM72A expression was found to positively correlate with the immune score in KIRC, KIRP, LGG, KIRC, thyroid carcinoma (THCA), UVM, and PCPG, but negatively correlated with the immune score in CESC, STAD, LUSC, UCEC, HNSC, READ, COAD, and ESCA." (PMID 36613817, 2022).
uterine cancer (1 paper, 2021). Primary or metastatic malignant neoplasm involving the uterine corpus and/or the cervix. "Investigation of the methylation status of FAM72A in non-neuronal tissues revealed that increased expression of FAM72A in lung and uterine cancer tissues appeared to be rather independent of its methylation status." (PMID 33804473, 2021). "Indeed, SRGAP2 itself shows no changes in its comparatively higher expression (with FAM72A) with slight differences in promoter methylation of SRGAP2 in breast, liver, lung, and uterine cancers." (PMID 33804473, 2021).
cancer (8 papers, 2021 to 2025). A tumor composed of atypical neoplastic, often pleomorphic cells that invade other tissues. "For instance, the expression of the Ki67 gene (MKI67), the putative proliferation marker, was found to be tightly associated with levels of FAM72A, B, and D across different cancers." (PMID 36613817, 2022). "We also identified that FAM72A was significantly less frequently mutated in HCC than in other cancers." (PMID 36483027, 2022). "High levels of FAM72A may promote mutations in antibody-related genes, and therefore, increased levels of FAM72A may stimulate cancer development, progression, or drug resistance by increasing the number of mutations." (PMID 36483027, 2022). "Our results suggest that the ability of FAM72A to induce UNG2 degradation contributes to neoplasia in a variety of cancer types by promoting mutagenic repair of genomic dUs." (PMID 40604025, 2025). "Of HCC patients, FAM72A was amplified in a lower proportion of tissues compared with pan-cancer patients." (PMID 36483027, 2022). "FAM72A activity was significantly higher in cancers than in normal tissue in tumors with increased FAM72A levels." (PMID 36613817, 2022). "Several public databases, including The Cancer Genome Atlas (TCGA) and the Genotype-Tissue Expression (GTEx), were used to determine expression levels and prognostic implications of FAM72A from the perspective of pan-cancer." (PMID 36613817, 2022). "The current study indicates that FAM72A has promise as a prognostic biomarker in various cancers, and FAM72A plays a vital role in the tumor immune microenvironment." (PMID 36613817, 2022). "The family with sequence similarity 72 Member A (FAM72A) is overexpressed in several types of cancer." (PMID 36613817, 2022). "To date, the evidence of FAM72A’s implications in cancer is very preliminary and lacks experimental validation." (PMID 36613817, 2022). "Our findings can be used as a source for other researchers interested in the role of FAM72A in cancers and to attract more attention to this potentially functionally important molecule." (PMID 36613817, 2022). "The family with sequence similarity 72 member A (FAM72A) protein has been identified as an effector of multiple pathological processes in many cancers." (PMID 36483027, 2022). "Accordingly, high levels of FAM72A predicted inferior outcomes in half of the cancer types using survival analysis (the Kaplan-Meier curve and univariate Cox regression model)." (PMID 36613817, 2022). "To investigate the potential function of FAM72A Pan-cancer, we carried out a gene set enrichment analysis (GSEA)." (PMID 36613817, 2022). "Under pathophysiological conditions, FAM72A is also expressed in various proliferating cancer cells." (PMID 34831023, 2021). "Family with sequence similarity 72 A (FAM72A) is a pivotal mitosis-promoting factor that is highly expressed in various types of cancer." (PMID 34831023, 2021). "There are certain advantages of using RNAi for cancer therapy including the ability to target any gene including FAM72A, low dosages, and extended inhibition after a single dose." (PMID 33804473, 2021). "The precise functions of FAM72A, B, and D in cancer still requires further investigation." (PMID 40604025, 2025). "Based on The Cancer Genome Atlas (TCGA) database, FAM72A was upregulated across 33 types of cancer." (PMID 36613817, 2022). "Hence, we aim to conduct a pan-cancer analysis to understand the role of FAM72A across 33 cancer types." (PMID 36613817, 2022). "We adopted this method to determine stromal and immune scores for samples across 33 cancer types and found that immune scores derived from the ESTIMATE algorithm were differentially correlated to FAM72A among different cancer types, and this was also the case for stromal cells." (PMID 36613817, 2022). "We first examine the endogenous expression levels of FAM72A in normal lung and cancer cell lines." (PMID 36613817, 2022).
cancer (continued). "According to a recent study, increased levels of FAM72A might stimulate cancer initiation and development and induce treatment resistance." (PMID 36483027, 2022). "Notably, CD274/PD-L1, PDCD1LG2/PD-L2, PDCD1/PD1, cytotoxic T lymphocyte-associated antigen 4 (CTLA4), T cell membrane protein 3 (TIM3; also known as HAVCR2), and lymphocyte activation gene 3 (LAG3) were correlated to FAM72A across different cancers." (PMID 36613817, 2022). "In addition, FAM72A is expressed at high levels in other cancers, such as gastrointestinal, breast, lung, liver, and ovarian cancers." (PMID 36483027, 2022). "In addition, further work is needed to assess whether FAM72A contributes to any additional functional activities, especially in cancer." (PMID 40604025, 2025). "FAM72A may also contribute to genome instability in cancer development because low levels of UNG2 as observed in FAM72A high cancers can lead to increased level of unprocessed genomic dUs, which is a source of replication stress that can interfere with replication fork progression." (PMID 40604025, 2025). "Furthermore, several TCGA-based bioinformatic studies indicated that FAM72A might be involved in cancer." (PMID 36613817, 2022). "The heatmap showed that the 15 CpG sites (located on B3GALNT1, C6orf97, FAM72A, FAM72B, LIFR, OSMR, ZNF264, and ZNF543) well‐distinguished CRC from adjacent normal tissues, WBCs, and 28 other types of cancer in TCGA, as well as 23 other types of cancer in GEO." (PMID 37649326, 2023). "Prognostic genes include LAS1L, SUPT4H1, FAM72A, C11orf31 and MRPS22, which play key roles in the biological mechanisms of cancer." (PMID 33976726, 2021). "This denotes that the cellular role of FAM72A is as a cooperative partner for genomic BER in order to ensure genome integrity and impede the formation of cancer." (PMID 34831023, 2021). "Our study here suggests that among the four FAM72 paralogues, only FAM72A can downregulate UNG2, and may explain the increased mutagenesis in cancers that overexpress FAM72A12." (PMID 40604025, 2025). "However, the effects of enhanced FAM72A gene expression on prognosis have not been systematically evaluated across different cancer types." (PMID 36613817, 2022).